DLD (dihydrolipoamide dehydrogenase)
Description:
Lipoamide dehydrogenase is a component of the glycine cleavage system as well as an E3 component of three alpha-ketoacid dehydrogenase complexes (pyruvate-, alpha-ketoglutarate-, and branched-chain amino acid-dehydrogenase complex). The 2-oxoglutarate dehydrogenase complex is mainly active in the mitochondrion. A fraction of the 2-oxoglutarate dehydrogenase complex also localizes in the nucleus and is required for lysine succinylation of histones: associates with KAT2A on chromatin and provides succinyl-CoA to histone succinyltransferase KAT2A. In monomeric form may have additional moonlighting function as serine protease. Involved in the hyperactivation of spermatazoa during capacitation and in the spermatazoal acrosome reaction (By similarity). The pyruvate dehydrogenase (PDH) complex catalyzes the overall conversion of pyruvate to acetyl-CoA and CO(2), and thereby links cytoplasmic glycolysis and the mitochondrial tricarboxylic acid (TCA) cycle (Probable). It contains multiple copies of three enzymatic components: pyruvate dehydrogenase (E1), dihydrolipoamide acetyltransferase (E2) and dihydrolipoamide dehydrogenase (E3) (Probable). The E3 subunit catalyzes reoxidation of the dihydrolipoyl moiety on lipoyl-bearing domains (LBDs) of E2 with NAD+ as the ultimate electron acceptor.
Synonyms: GCSL; LAD; PHE3; DLDH; E3; OGDC-E3; DLDD
Tractability: Small molecule: a structure with a bound ligand is known; it has a high-quality binding pocket; it belongs to a druggable protein family. PROTAC: ubiquitination databases record sites on it; its protein half-life has been measured.
Target class: Enzyme; Oxidoreductase
Gene: Protein-coding gene on chromosome 7 (107,891,162 to 107,931,730, forward strand). Ensembl gene ENSG00000091140.
Subcellular location: Mitochondrion matrix; Nucleus; Cell projection, cilium, flagellum; Cytoplasmic vesicle, secretory vesicle, acrosome
Subcellular location (Human Protein Atlas): Mitochondria; Cytokinetic bridge; Nucleoplasm; Primary cilium; Principal piece
Pathways (Reactome):
Metabolism: BCKDH synthesizes BCAA-CoA from KIC, KMVA, KIV; Branched-chain amino acid catabolism; Glycine degradation; OADH complex synthesizes glutaryl-CoA from 2-OA; OGDH complex synthesizes succinyl-CoA from 2-OG; PDH complex synthesizes acetyl-CoA from PYR; Regulation of pyruvate dehydrogenase (PDH) complex
Disease: Branched-chain ketoacid dehydrogenase kinase deficiency; H139Hfs13* PPM1K causes a mild variant of MSUD; Loss-of-function mutations in DBT cause MSUD2; Loss-of-function mutations in DLD cause MSUD3/DLDD
Metabolism of proteins: Mitochondrial protein degradation
Signal Transduction: Signaling by Retinoic Acid
Gene Ontology:
Molecular function: dihydrolipoyl dehydrogenase (NADH) activity; protein binding; flavin adenine dinucleotide binding; oxidoreductase activity; oxidoreductase activity, acting on a sulfur group of donors, NAD(P) as acceptor
Biological process: 2-oxoglutarate decarboxylation to succinyl-CoA; branched-chain alpha-keto acid decarboxylation to branched-chain acyl-CoA; branched-chain amino acid catabolic process; L-lysine catabolic process; pyruvate decarboxylation to acetyl-CoA; 2-oxoglutarate metabolic process; tricarboxylic acid cycle
Cellular component: branched-chain alpha-ketoacid dehydrogenase complex; mitochondrion; nucleoplasm; nucleus; oxoadipate dehydrogenase complex; oxoglutarate dehydrogenase complex; pyruvate dehydrogenase complex; mitochondrial matrix; acrosomal matrix; acrosomal vesicle; cilium; motile cilium
Genetic constraint (gnomAD): Loss-of-function variants: 27 observed, 51.2 expected, observed/expected ratio (o/e) 0.53, 90% interval 0.39 to 0.73. The upper end of that interval is the gene's LOEUF score, 0.73, which puts it in group 2 of 6, group 1 being the genes least tolerant of losing a copy. Missense variants: 456 observed, 554.79 expected, observed/expected ratio (o/e) 0.82, 90% interval 0.76 to 0.89. Synonymous variants: 180 observed, 184.51 expected, observed/expected ratio (o/e) 0.98, 90% interval 0.86 to 1.1.
Gene-disease validity (ClinGen):
ClinGen rates the evidence that DLD causes each of these diseases.
Leigh syndrome (autosomal recessive): Definitive. A progressive neurological disease defined by specific neuropathological features associating brainstem and basal ganglia lesions.
pyruvate dehydrogenase E3 deficiency (autosomal recessive): Definitive. Pyruvate dehydrogenase E3 deficiency is a very rare subtype of pyruvate dehydrogenase deficiency (PDHD) characterized by either early-onset lactic acidosis and delayed development, later-onset neurological dysfunction or liver disease.
Homologues: Orthologues: chimpanzee DLD (100% identical), dog DLD (98% identical), macaque DLD (97% identical), mouse Dld (95% identical), pig DLD (93% identical), rat Dld (93% identical), tropical clawed frog dld (84% identical), zebrafish dldh (83% identical), Caenorhabditis elegans dld-1 (69% identical), Drosophila melanogaster CG7430 (67% identical). Paralogues in human: TXNRD1 (31% identical), TXNRD3 (31% identical), TXNRD2 (29% identical), GSR (28% identical), AIFM3 (19% identical), AIFM1 (17% identical), PYROXD1 (15% identical).
Diseases named in the same sentence as DLD in open-access papers:
DLD is named in the same sentence as 106 diseases in open-access papers, as found by Europe PMC text mining. Sharing a sentence is not in itself a finding about the gene and the disease. The quoted sentences say what the papers report.
breast carcinoma (13 papers, 2022 to 2025). "In the cohort study, high expression of LIAS, FDX1, LIPT1, DLD, PDH1, and ATP7B, coupled with low CDKN2A expression, was associated with favorable RFS in patients with estrogen receptor-positive early breast cancer (ER+ EBC)." (PMID 39867656, 2024). "Based on these results, we speculate that DLD possibly is the key regulated gene in HER2+ breast cancer patients." (PMID 35935587, 2022). "However, in DLD, as a mitochondrial-related gene, its roles in breast cancer are poorly understood." (PMID 35935587, 2022). "In the GSE145548 cohort, the downregulation of ATF2 in MCF7 breast cancer cells resulted in substantial changes in the expression of cuproptosis regulators (DLST, GCSH, PDHA1, LIPT1, and DLD)." (PMID 39867656, 2024). "In the GSE145548 cohort, knockdown of ATF2 in breast cancer cells MCF7 resulted in the dramatic change of cuproptosis regulators (DLST, GCSH, PDHA1, LIPT1 and DLD)." (PMID 36733399, 2022). "Prognosis analysis revealed poor OS and RFS rates in breast cancer patients with elevated levels of CDKN2A and PDHA1 and low levels of MTF1, DLD, LIPT1, and FDX1." (PMID 36312586, 2022). "Multiomics approaches were used to create a cuproptosis-related signature with six genes (DKN2A, MTF1, PDHA1, DLD, LIPT1, and FDX1) for breast cancer." (PMID 36312586, 2022). "In conclusion, multiomics approaches were conducted to develop a cuproptosis-related signature with six genes (DKN2A, MTF1, PDHA1, DLD, LIPT1, and FDX1) for breast cancer." (PMID 36312586, 2022). "We then constructed a cuproptosis-related signature with six genes (DKN2A, MTF1, PDHA1, DLD, LIPT1, and FDX1) for breast cancer, which predicted the OS rate with an accuracy that ranged from medium to high." (PMID 36312586, 2022). "FDX1 (P < 1E‐12), LIAS (P = 2.22E‐16), LIPT1 (P < 1E‐12), DLD (P < 5.46E‐09), DLAT (P = 3.14E‐02), PDHA1 (P = 1.15E‐07), MTF1 (P = 1.07E‐09), and GLS (P = 2.48E‐05) were downregulated in breast cancer, while PDHB (P = 5.04E‐07) and CDKN2A (P = 1.62E‐12) were upregulated." (PMID 39432636, 2024). "After internalization by mouse 4T1 breast cancer cells, Cu+ coupled with ES induced DLAT oligomerization and the downregulation of Fe‒S cluster proteins, such as ferredoxin 1 (FDX1) and dihydrolipoamide dehydrogenase (DLD), ultimately leading to cuproptosis." (PMID 39554839, 2024). "We analyzed the expression pattern of CRGs in breast cancer tissues and non-tumor tissues based on TCGA and GTEx dataset, illustrating that CDKN2A, DLD, DLAT, MTF1 and PDHB expression were significantly elevated in breast cancer compared with their normal tissues." (PMID 36518756, 2022). "Additionally, it was discovered via research of the impact of gene expression patterns on overall survival in breast cancer that those expressing high levels of ATP7A, DBT, DLAT, DLD, GLS, PDHA1, and SLC31A1 had a bad prognosis." (PMID 36059516, 2022). "Another vital discovery of our research was that we developed a cuproptosis-related prognostic signature containing six genes (CDKN2A, MTF1, PDHA1, DLD, LIPT1, and FDX1) for breast cancer, which predicted the OS rate with an accuracy that ranged from medium to high." (PMID 36312586, 2022). "As cuproptosis-promoting genes, FDX1, LIAS, LIPT1, DLD, DLAT, and PDHA1 were under-expressed in breast cancer; at the same time, CDKN2A, which inhibited cuproptosis, was over-expressed in breast cancer, suggesting that cuproptosis might involve in the protective mechanism of BRCA." (PMID 39432636, 2024).
melanoma (12 papers, 2022 to 2023). A malignant, usually aggressive tumor composed of atypical, neoplastic melanocytes. "In melanoma cells, it has been proved that the downregulation of DLD can alternate the energy metabolism of mitochondria through decreasing downstream metabolites of the TCA cycle, therefore inducing death via autophagy." (PMID 37143115, 2023). "The downregulation of DLD expression was shown to increase intracellular ROS production and reduce mitochondrial membrane potential, thereby inducing autophagic cell death in melanoma cells and significantly inhibiting tumor proliferation in vivo." (PMID 37152283, 2023). "It is noteworthy that a pivotal role of this enzyme in melanoma progression was recently suggested by Yumman and colleagues, who demonstrated that DLD down-regulation induced autophagy and inhibited proliferation of melanoma cells." (PMID 36431901, 2022). "Inhibition of DLD in melanoma cells resulted in an increased ratio of NAD+ to NADH, with a concomitant reduction in TCA cycle intermediates, increased ROS production, and enhanced autophagic cell death." (PMID 36278487, 2022). "In addition, it is reported that suppression of DLD expression inhibits melanoma growth and tumor proliferation by increasing intracellular reactive oxygen species (ROS) production and thereby inducing autophagy cell death." (PMID 36865349, 2023). "For example, downregulation of DLD in melanoma could inhibit cell proliferation by regulating energy metabolism, while DLD overexpression in head and neck cancer (HNC) cells could induce ferroptosis." (PMID 35935587, 2022). "We found that the expression of FDX1, LIAS, LIPT1, DLD, DLAT, MTF1, and CDKN2A were significantly lower in melanoma than in normal tissues." (PMID 36824136, 2023). "It has been shown that DLD downregulation significantly increases α-ketoglutarate and decreases succinate, and DLD inhibition can decrease TCA cycle downstream metabolites, leading to altered mitochondrial energy metabolism in melanoma." (PMID 38077227, 2023). "Therefore, our proteomic, structural, and functional results strongly suggest that DLD, as a key enzyme in several multi-enzymatic complexes involved in mitochondrial energy metabolism, may represent a novel and suitable target for the treatment of BRAFi-resistant melanoma." (PMID 36431901, 2022). "DLD inhibition could have resulted in lower levels of TCA cycle downstream metabolites, and downmodulation of DLD promoted autophagy in melanoma cells, as well as inhibiting tumor growth and proliferation in vivo." (PMID 36046242, 2022). "Evidence from other studies has revealed that DLD downregulation may affect mitochondrial metabolism, which reduces the levels of downstream metabolites in the TCA cycle, induces melanoma cell death, and inhibits tumor progression in humans by promoting ROS production and altering energy metabolism." (PMID 37113760, 2023).
colorectal cancer (5 papers, 2022 to 2025). A primary or metastatic malignant neoplasm that affects the colon or rectum. "Taken together, miR‐653 negatively regulates the expression of DLD, therefore promoting cell proliferation and inhibiting apoptosis of colorectal cancer." (PMID 37334893, 2023). "What's more, we demonstrated that miR‐653 was highly expressed in colorectal cancer, closely correlated with clinicopathological features, and promoted cell proliferation by negatively regulating the expression of DLD." (PMID 37334893, 2023). "We also found that PDHB and DLD were differentially expressed in colorectal cancer, while FDX1 was distinctly expressed in lung adenocarcinoma." (PMID 36506302, 2022). "In addition, miR‐653 was highly expressed in colorectal cancer tissues, closely correlated with the clinicopathological features, negatively regulated the expression of DLD, promoted cell proliferation, and inhibited apoptosis of colorectal cancer." (PMID 37334893, 2023). "The study revealed that, compared to normal tissues, genes FDX1, DLD, DBT, DLST, and DLAT were significantly downregulated in colorectal cancer tissues, while LIPT1, GCSH, and ATP7B genes were upregulated." (PMID 40276654, 2025).
head and neck cancer (5 papers, 2020 to 2025). A primary or metastatic malignant neoplasm affecting the head and neck. "The relationship between TCA cycle and ferroptosis has been underlined by a recent study which found the flavoprotein dihydrolipoamide dehydrogenase (DLD) responsible for the cysteine deprivation-induced ferroptosis in head and neck cancer cell lines." (PMID 33406703, 2021). "α-Ketoglutarate dehydrogenase (α-KGDH) converts α-KG to succinyl-CoA, and when its E3 component DLD is silenced, lipid peroxidation and cystine deprivation-induced ferroptosis in head and neck cancer cells is inhibited via a mechanism involving glutaminolysis." (PMID 40083691, 2025). "In central nervous system (CNS) tumors, the cuprotosis-related gene dihydrolipoamide dehydrogenase (DLD) has been demonstrated to induce ferroptosis in head and neck cancer cells by regulating glutamine metabolism." (PMID 37713112, 2024). "In head and neck cancer (HNC), dihydrolipoamide dehydrogenase (DLD) gene silencing blocked cystine deprivation-induced ferroptosis, displaying decreased lipid ROS and mitochondrial iron levels." (PMID 33511116, 2020).
lung adenocarcinoma (5 papers, 2022 to 2023). A carcinoma that arises from the lung and is characterized by the presence of malignant glandular epithelial cells. "A study has studied the crucial role of cuproptosis-related genes (CRGs) in lung adenocarcinoma and found that MTF1, SLC31A1, FDX1 and DLD were associated with the tumor microenvironment and immune responses in lung adenocarcinoma." (PMID 37380924, 2023). "In this research, samples of lung adenocarcinoma were interrogated with cuproptosis-related genes, among which high expression of DLD, DLAT, PHDA1, PHDB, and CDKN2A were correlated with poor OS, while high expression of MTF1 was correlated with longer OS compared with the MTF1 low expression." (PMID 36003780, 2022). "To confirm the roles of lncRNA UCA1, miR-1-3p and DLD in LUAD, we further verified their differential expressions in normal lung epithelial cells (BEAS-2B) and different lung adenocarcinoma cell lines (A549 and H1299) by in vitro cell experiments." (PMID 36110528, 2022).
Alzheimer disease (4 papers, 2014 to 2023). A progressive, neurodegenerative disease characterized by loss of function and death of nerve cells in several areas of the brain leading to loss of cognitive function such as memory and language. "In this study, we found that DLD was significantly up-regulated in the bradyzoites infection group, which may provide a new insight for explaining the mechanism of T. gondii infection-induced Alzheimer’s disease." (PMID 37721957, 2023).
branched-chain ketoaciduria (4 papers, 2018 to 2022). "Dehydrogenases also play an important role in mitochondrial function, where for instance, mutations of the DLD gene are associated with branched-chain ketoaciduria and Leigh disease." (PMID 30061171, 2018). "Maple syrup urine disease (MSUD) is an autosomal recessive inherited metabolic disorder caused by mutations in the BCKDHA, BCKDHB, DBT, and DLD genes." (PMID 29740478, 2018).
diabetes (4 papers, 2019 to 2024). "DLD (dihydrolipoamide dehydrogenase), a member of the class I pyridine nucleotide-disulfide oxidoreductase family, acts as a dehydrogenase that plays a key role in pyruvate oxidation and tetrahydrofolate metabolism and serves as a potential marker of diabetes in human myocytes." (PMID 35445133, 2022). "In conclusion, there is a growing recognition of the impact of PDC and its constituent components, DLAT, DLD, PDHA1, and PDHB, on diabetes." (PMID 38904034, 2024).
gastric cancer (3 papers, 2016 to 2023). A primary or metastatic malignant neoplasm involving the stomach. "We verified the expression of DLD in gastric cancer cell lines by cellular assays and found that the expression of DLD was significantly higher in gastric cancer cell lines (MKN-45, AGS, SGC7901) than in gastric epithelial cells (GES-1)." (PMID 38077227, 2023). "High expression of DLD in gastric cancer cells was identified by cellular experiments." (PMID 38077227, 2023). "Therefore, high expression of LDH and DLD is a crucial factor for the development and progression of gastric cancer, and H. pylori infection promotes the expression of these two genes in gastric cancer tissues." (PMID 26745502, 2016). "Among them, DLD and PDHA1 were differentially expressed in colon cancer, and DLAT, DLD, and PDHA1 were differentially expressed in gastric cancer and liver cancer." (PMID 36960059, 2023).
glioma (3 papers, 2022 to 2023). A benign or malignant brain and spinal cord tumor that arises from glial cells (astrocytes, oligodendrocytes, ependymal cells). "In glioma patients, the levels of CDKN2A, FDX1, DLD, DLAT, LIAS, LIPT1, and PDHA1 were significantly associated with the OS, disease-specific survival, and progression-free interval." (PMID 36579333, 2022). "Further analysis of the relationship between CRGs and the prognosis of gliomas revealed that high expression of FDX1, DLD, DLAT, and LIPT1 was associated with poorer survival in glioma patients, and high expression of CDKN2A and PDHA1 was significantly associated with better survival in gliomas." (PMID 36915038, 2023). "Furthermore, Cox regression analysis in the TCGA database showed that FDX1, LIPT1, DLD, DLAT, SLC31A1, ATP7A, and DLST might be risk factors; however, LIAS, ATP7B, and GCSH were significant preventive factors for gliomas." (PMID 37515314, 2023). "Only GLS and ATP7B had low expression levels in glioma patients; however, others, including FDX1, LIPT1, DLD, and SLC31A1, were overexpressed." (PMID 37515314, 2023). "We performed receiver operating characteristic curve (ROC) analyses to assess whether various CRG levels aided glioma detection; the areas under the curves (AUCs) were >0.9 for CDKN2A, FDX1, DLD, and PDHB." (PMID 36579333, 2022).
Leigh disease (3 papers, 2013 to 2024). "Exome capture was performed in a boy who developed Leigh disease following a gastroenteritis and had combined PDH and α-KGDH deficiency with a unique amino acid profile that partly ressembled E3 subunit (dihydrolipoamide dehydrogenase / DLD) deficiency." (PMID 24341803, 2013).
lung carcinoma (3 papers, 2022 to 2023). "We speculate that DLD gene alterations play an important role in the development of lung cancer and thus affect patient prognosis." (PMID 38077227, 2023). "Intriguingly, based on our single-cell RNA-seq data, we classified TME cells in lung cancer into seven main cell types and discovered that FDXL, DLD, SLC3A1, and PDHA1 were differentially expressed in macrophages." (PMID 36263125, 2022). "In addition to CDKN2A, genes, including DLD, LIPT1, GLS, PDHB, and PDHA1, also have significant CNVs, indicating the heterogeneity of lung cancer tissue." (PMID 36712848, 2022).